TCOF1 (treacle ribosome biogenesis factor 1)
Description:
Nucleolar protein that acts as a regulator of RNA polymerase I by connecting RNA polymerase I with enzymes responsible for ribosomal processing and modification. Required for neural crest specification: following monoubiquitination by the BCR(KBTBD8) complex, associates with NOLC1 and acts as a platform to connect RNA polymerase I with enzymes responsible for ribosomal processing and modification, leading to remodel the translational program of differentiating cells in favor of neural crest specification.
Synonyms: treacle; TCS; MFD1; TCS1
Tractability: PROTAC: UniProt records ubiquitination sites on it; ubiquitination databases record sites on it; its protein half-life has been measured.
Gene: Protein-coding gene on chromosome 5 (150,357,629 to 150,400,491, forward strand). Ensembl gene ENSG00000070814.
Subcellular location: Nucleus, nucleolus
Subcellular location (Human Protein Atlas): Nucleoli fibrillar center
Gene Ontology:
Molecular function: protein binding; protein heterodimerization activity; protein-macromolecule adaptor activity; RNA binding; scaffold protein binding
Biological process: neural crest cell development; neural crest formation; regulation of translation; nucleolar large rRNA transcription by RNA polymerase I; ribosome biogenesis; skeletal system development
Cellular component: fibrillar center; nucleolus
Genetic constraint (gnomAD): Loss-of-function variants: 33 observed, 153.15 expected, observed/expected ratio (o/e) 0.22, 90% interval 0.16 to 0.29. The upper end of that interval is the gene's LOEUF score, 0.29, which puts it in group 1 of 6, group 1 being the genes least tolerant of losing a copy. Missense variants: 1,728 observed, 1,911.5 expected, observed/expected ratio (o/e) 0.9, 90% interval 0.87 to 0.94. Synonymous variants: 789 observed, 767.89 expected, observed/expected ratio (o/e) 1.03, 90% interval 0.97 to 1.09.
Gene-disease validity (ClinGen):
ClinGen rates the evidence that TCOF1 causes each of these diseases.
Treacher-Collins syndrome (autosomal dominant): Definitive. A congenital disorder of craniofacial development characterized by bilateral symmetrical oto-mandibular dysplasia without abnormalities of the extremities, and associated with several head and neck defects.
Homologues: Orthologues: chimpanzee TCOF1 (99% identical), macaque TCOF1 (91% identical), dog TCOF1 (67% identical), rabbit TCOF1 (66% identical), guinea pig TCOF1 (62% identical), pig TCOF1 (55% identical), rat Tcof1 (54% identical), mouse Tcof1 (53% identical), zebrafish tcof1 (10% identical).
Diseases named in the same sentence as TCOF1 in open-access papers:
TCOF1 is named in the same sentence as 86 diseases in open-access papers, as found by Europe PMC text mining. Sharing a sentence is not in itself a finding about the gene and the disease. The quoted sentences say what the papers report.
Treacher-Collins syndrome (65 papers, 2009 to 2026). "For example, Lis1 plays a role in lissencephaly, TCOF1 is associated with Treacher Collins Syndrome (TCS), and TBL1X participates in Ocular Albinism with late-onset sensorineural deafness (OASD)." (PMID 41312386, 2025). "Given the role of TCOF1 in ribosome biogenesis and craniofacial development, this mutation is associated with Treacher Collins syndrome, a disorder characterized by craniofacial abnormalities due to defects in neural crest cell function." (PMID 40282387, 2025). "Our study found two novel pathogenic variants of TCOF1 gene and clarified the etiology of Treacher Collins syndrome." (PMID 38444283, 2024). "The most well-known cause of craniofacial anomalies like these is Treacher-Collins syndrome, which presents with micrognathia and microtia due to mutations in the TCOF1 gene." (PMID 39139328, 2024). "This is the first case report regarding a novel pathogenic variant within exon 17 of the Treacle Ribosome Biogenesis Factor 1 (TCOF1) gene causing Treacher Collins syndrome." (PMID 39280575, 2024). "The mode of inheritance for Treacher Collins syndrome (TCS) associated with TCOF1 mutations is autosomal dominant, although very rare cases of autosomal recessive mutations have been observed." (PMID 39280575, 2024). "The clinical data of two patients with Treacher Collins syndrome caused by TCOF1 gene variation were retrospectively analyzed." (PMID 38444283, 2024). "More specifically, mutations in POLR1A cause Acrofacial Dysostosis Cincinnati type (AFDCin), whereas mutations in POLR1B, POLR1C and POLR1D and the Pol I associated protein, TCOF1/TREACLE lead to Treacher Collins Syndrome (TCS)." (PMID 37639467, 2023). "Autosomal dominant mutations in TCOF1 cause Treacher Collins Syndrome, which involves craniofacial deformities and conductive hearing loss due to abnormal neural crest cell development." (PMID 36656851, 2023). "Among these diseases, the etiology of Treacher Collins syndrome is a mutation in the TCOF1 gene, encoding the cofactor Treacle of RNA polymerase I, which transcribes rRNA." (PMID 36830657, 2023). "Mutations in TCOF1 cause Treacher Collins syndrome, a congenital craniofacial disorder associated with tissue-specific disruptions in ribosome biogenesis." (PMID 38099650, 2023). "The majority of Treacher Collins Syndrome cases are caused by truncating mutations that result in TCOF1 haploinsufficiency." (PMID 36656851, 2023). "Treacher Collins syndrome (TCS) is caused by various mutations in the genes TCOF1, POLR1B, POLR1C, or POLR1D." (PMID 36271492, 2022). "Treacle is the protein encoded by the TCOF1 gene, which is predominantly mutated in Treacher Collins Syndrome (TCS)." (PMID 35646927, 2022). "Previously, TCOF1 variants with premature-termination codons were associated with an autosomal dominant craniofacial development disorder, the Treacher Collins Syndrome." (PMID 33937142, 2021). "Here we describe three novel TCOF1 mutations found in unrelated patients with Treacher Collins syndrome." (PMID 34580285, 2021). "Mutations in the TCOF1 gene cause Treacher Collins syndrome (TCS), which is an autosomal dominant disorder characterized by abnormalities of craniofacial development that arises during early embryogenesis." (PMID 33498741, 2021). "To date, the molecular basis of Treacher Collins syndrome, including the specific role of TCOF1 mutations, have been extensively studied." (PMID 33804586, 2021). "Another factor that was reported to participate in DNA damage-induced silencing of nucleolar transcription is Treacle (also known as TCOF1), a nucleolar factor implicated in ribosome biogenesis and mutated in Treacher Collins syndrome." (PMID 31114877, 2019).
Treacher-Collins syndrome (continued). "Treacher Collins Syndrome is further characterized by an environmental component that strongly affects the phenotypic strength of identical TCOF1 mutations across patients." (PMID 29999490, 2018). "Related to this, mutations in the Treacher Collins Syndrome Treacle Protein (TCOF1) gene cause Treacher Collins Syndrome (TCS), which, amongst other defects, is associated with microcephaly." (PMID 25729350, 2015). "Increased tissue specific apoptosis is associated with disruption of several ribosome biogenesis factors, including Tcof1, the protein that is mutated in Treacher-Collins syndrome." (PMID 25756904, 2015). "Together, these results suggest that strategies developed to decrease the ubiquitination of residual non-mutant TCOF1 could diminish severity of individuals with Treacher Collins syndrome caused by loss of function mutations in Tcof1." (PMID 32916911, 2020). "Mutations in TCOF1 are the major cause of Treacher Collins Syndrome, a craniofacial disease that is characterized by aberrant neural crest specification and survival." (PMID 29999490, 2018). "Underscoring the importance of this regulatory circuit for human biology, mutations in TCOF1 account for ~90% of cases of the craniofacial disease Treacher Collins Syndrome, while additional transcription factor binding sites in the promoter of KBTBD8 drive melanoma, a cancer of neural crest origin." (PMID 29999490, 2018). "The TCOF1 gene is mutated in Treacher Collin's syndrome, a congenital craniofacial syndrome." (PMID 26792133, 2016). "Finally, we note the highly surprising finding of a homozygous nonsense mutation in TCOF1 causing severe Treacher-Collins syndrome while the carrier parents are completely normal clinically." (PMID 26112015, 2015). "Haploinsufficiency of TCOF1 in humans is associated with Treacher Collins syndrome, characterized by impaired craniofacial development as well as ear defects leading to deafness, and the absence of TCOF1-null mice or humans suggests that knockout is embryonic lethal." (PMID 24743236, 2014). "Furthermore our work has important implications in the pathogenesis of neurodevelopmental disease as individuals with mutations in TCOF1 that present with Treacher Collins syndrome can also exhibit microcephaly and psychomotor delay as part of the condition." (PMID 22479190, 2012). "In the nucleolus, NOLC1 forms a complex with its paralogue TCOF1, a protein mutated in ribosomopathy manifested as Treacher-Collins Syndrome (TCS)." (PMID 36411431, 2022). "It was intriguing to us that many of the observed phenotypes observed in fan mutant zebrafish have also been reported in humans (and mice) with mutations in TCOF1/Treacle, the gene commonly mutated in Treacher-Collins Syndrome (TCS)." (PMID 24497835, 2014). "However, Treacher Collins syndrome (which occurs primarily as a consequence of mutations in TCOF1) is typically regarded as a cranioskeletal disorder and a role for TCOF1/Treacle in cortical neurogensis and the regulation of brain size has not been previously explored." (PMID 22479190, 2012). "BACKGROUND: To elucidate the prenatal diagnostic challenges, genetic landscape, and clinical outcomes of Treacher Collins syndrome (TCS), focusing on the role of TCOF1 variants, prenatal ultrasound findings, and counselling implications." (PMID 41857598, 2026). "Treacher Collins Syndrome (TCS) (or Franceschetti Syndrome in other words) is a rare congenital deformity with a strong genetic background—with four genes being responsible (TCOF1, POLR1D, POLR1C and POLR1B)." (PMID 40649114, 2025). "A classic example of this is Treacher Collins syndrome (TCS), which, although primarily caused by mutations in treacle ribosome biogenesis factor 1 (TCOF1), is characterized by considerable variability in the severity of mandibulofacial dysostosis." (PMID 40699891, 2025).
Treacher-Collins syndrome (continued). "Two cases of Treacher Collins syndrome with TCOF1(OMIM:606847) gene variations were reported in the article, with clinical characteristics, gene variants and the etiology." (PMID 38444283, 2024). "We also enriched the phenotypic spectrum of Treacher Collins syndrome and TCOF1 gene variation spectrum in the Chinese population, and provided the basis for clinical diagnosis, treatment and genetic counseling." (PMID 38444283, 2024). "TCOF1 was initially found as a gene related to Treacher Collins syndrome (TCS), a rare genetic disorder characterized by severe craniofacial defects, external ear deformation, and hearing impairment." (PMID 35093935, 2022). "Haploinsufficiency of TCOF1 results in Treacher Collins syndrome (TCS), one of the most severe congenital disorder of craniofacial development, highlighting its importance in cell proliferation and growth at the developmental stage." (PMID 34718356, 2022). "TCOF1 was initially discovered as a gene involved in Treacher Collins syndrome, a rare genetic disorder characterized by severe craniofacial deformations." (PMID 33804586, 2021). "TCOF1 was initially discovered as a gene involved in the Treacher Collins syndrome, a rare genetic disorder characterized by severe craniofacial deformations." (PMID 33804586, 2021). "Pathogenic variants in the TCOF1 but also the POLR1D and POLR1C genes have been previously associated with Treacher Collins syndrome (TCS) types 1–3, respectively." (PMID 33262786, 2020). "For example, previous studies found two synonymous mutations in TCOF1 and MPZ gene causing Charcot-Marie-Tooth disease type 1b and Treacher Collins syndrome." (PMID 28812016, 2017). "Treacher Collins syndrome (TCS) is caused by mutations in genes involved in rRNA transcription, such as the Treacher Collins-Franceschetti syndrome 1 (TCOF1) and POLR1D and POLR1C genes, which encode subunits of RNA polymerase I and III (PolI/III)." (PMID 26398160, 2015). "Mutations in nucleolar proteins have been found to be causative for a variety of human craniofacial syndromes including Treacher-Collins Syndrome (TCS), often caused by mutations in TCOF1, which also plays important roles in ribosome biogenesis." (PMID 24497835, 2014). "Treacher Collins syndrome (TCS) is an autosomal dominant disorder of craniofacial development, and mutations in the TCOF1 gene are responsible for over 90% of TCS cases." (PMID 22295061, 2012). "Notably, several genes involved in the craniofacial-biased disease Treacher Collins syndrome, TCOF1, POLR1C, and POLR1D, were low-scoring genes found to be expressed at high levels in virtually all tissues (Gini scores 0.23, 0.19, and 0.15 respectively)." (PMID 37532691, 2023). "While TCOF1 is known to cause congenital HL as part of Treacher-Collins syndrome, it has not previously been reported to increase risk of adult-onset HL." (PMID 36656851, 2023). "The TCOF1 gene has been cloned by the Treacher Collins Syndrome Collaborative Group2." (PMID 34580285, 2021). "The role of TCOF1 dysfunction in Treacher Collins syndrome is well documented." (PMID 33804586, 2021). "TCOF1 codes for a nucleolar phosphoprotein known as Treacle." (PMID 25729350, 2015). "Mutations in genes encoding the two RNA Pol I subunits, POLR1C and POLR1D, and in the nucleolar protein Treacher Collins-Franceschetti syndrome 1 (TCOF1, also known as treacle) cause the craniofacial disorder, Treacher Collins syndrome (OMIM 248390, OMIM 613717 and OMIM 154500)." (PMID 24040563, 2013).
Treacher-Collins syndrome (continued). "An extensive literature review of known mutations for exon 17 in the TCOF1 gene revealed no previous case reports for this specific mutation in TCOF1 exon 17, c.2689A>T (p.Arg897*), which is a novel pathogenic variant to cause Treacher Collins syndrome in our neonate." (PMID 39280575, 2024). "The identification of causative mutations in the TCOF1 gene (85% of the cases), but also in the RNA polymerase I (Pol I) subunits POLR1C, POLR1D and recently, POLR1B strongly suggests that perturbation of ribosome biogenesis is the underlying cause of Treacher Collins Syndrome." (PMID 35646927, 2022). "Treacher-Collins syndrome (TCS, OMIM# 154500, typically TCOF1 mutations) is characterized primarily by craniofacial defects." (PMID 27784267, 2016). "Treacher-Collins syndrome (TCS), an autosomal dominant congenital disorder of craniofacial development, characterized by mandibulofacial dysostosis including cleft palate and hypoplasia of the facial bones, is most commonly associated with mutations in the TCOF1 gene." (PMID 24497835, 2014). "We assessed the potential of the derived NC population to model the neurocristopathy, Treacher Collins Syndrome (TCS), using small interfering RNA (siRNA) knockdown of TCOF1 and by creating different TCOF1+/− HPSC lines through CRISPR/Cas9 technology." (PMID 30375284, 2019). "Furthermore, Treacher-Collins syndrome, a disease affecting only the cranial bone formation but not the rest of the skeleton, is caused by mutations in the ribosomal DNA transcription regulator Tcof1, despite the universal expression of Tcof1 in embryonic and adult tissues." (PMID 37378024, 2023). "It was, however, not until 1996 that the TCOF1 gene was identified by positional cloning by the Treacher Collins Collaborative Group." (PMID 35646927, 2022). "In families no 1–3, we found three novel heterozygous variants in the TCOF1 that gave rise to the most well-characterized MFD, i.e., Treacher Collins syndrome (TCS) type 1 (TCS1, MIM:154500)." (PMID 33262786, 2020).
hearing loss (4 papers, 2022 to 2024). "It has been reported that about 50% of TCS patients have different degrees of bilateral conductive hearing loss, which is related to changes in the internal structure of the ear caused by TCOF1 gene variation." (PMID 38444283, 2024). "As a specific example, we identify one gene–TCOF1, responsible for a syndromic form of congenital hearing loss–in which deleterious variants are also associated with adult-onset hearing loss." (PMID 36656851, 2023). "The remaining gene variants in CEACAM16, COL11A1, COL9A2, DIAPH1, TCOF1 were tested for segregation with the hearing loss phenotype in the extended family." (PMID 35292975, 2022).
deafness (3 papers, 2011 to 2021). An inherited or acquired condition characterized by the complete loss of the ability to hear from one or both ears. "During inner ear development, many genes causing IEM and deafness have been identified, including SLC26A4, EYA1, FGFR3, and TCOF1." (PMID 21961810, 2011).
triple-negative breast carcinoma (3 papers, 2022 to 2025). An invasive breast carcinoma which is negative for expression of estrogen receptor (ER), progesterone receptor (PR), and human epidermal growth factor receptor 2 (HER2). "TCOF1 depletion in triple-negative breast cancer patients significantly inhibited the growth and invasiveness of triple-negative breast cancer cells." (PMID 37091789, 2023). "Functionally, TCOF1 (Treacle) is involved in ribosome biogenesis, mitotic progression, and DNA damage response (Grzanka and Piekiełko-Witkowska, 2021), and also functions as a prognostic marker in triple-negative breast cancer." (PMID 41446278, 2025).
breast carcinoma (2 papers, 2022). "Whereas TCOF1 mRNA is upregulated in 32% TNBCs, its expression is underrepresented in other subtypes of breast cancer." (PMID 34718356, 2022). "In particular, high TCOF1 expression in TNBC or basal-like breast cancer resulted in a significant shorter survival than those with low TCOF1 expression (p = 0.011 and 0.013, respectively)." (PMID 34718356, 2022). "Compared with normal tissues, expression of TCOF1 total protein was higher in breast cancer (BC), colon cancer (CC), ovarian cancer (OC), CCRCC, and LUAD, but not in UCEC." (PMID 35093935, 2022). "To examine its effect on the binding of BRD4 to TCOF1 super-enhancer and TCOF1 expression, we performed ChIP-qPCR and immunoblotting in JQ1- or dimethyl sulfoxide-treated breast cancer cells." (PMID 34718356, 2022). "In summary, we leveraged the multiomic profiling on super-enhancers to uncover a novel oncogenic gene, TCOF1, in modulating CSC properties of breast cancer." (PMID 34718356, 2022). "Furthermore, by interrogating clinical data sets containing 959 breast cancer cases, we found that high expression of TCOF1 was significantly associated with tumour grade (p < 0.001) and TNM stage (p < 0.001), suggesting that TCOF1 may enhance tumour growth in TNBC patients." (PMID 34718356, 2022). "To investigate whether TCOF1 is overexpressed in TNBC, we analysed a data set of breast cancer from The Cancer Genome Atlas Project." (PMID 34718356, 2022).
colorectal cancer (2 papers, 2013 to 2022). A primary or metastatic malignant neoplasm that affects the colon or rectum. "TCOF1 expression was significantly correlated with prognosis in seven cancer types: BC, uveal melanoma (UVM), liposarcoma, renal-cell carcinoma (RCC), glioma, meningioma, and colorectal cancer (CRC)." (PMID 35093935, 2022).